RNU6-1282P (RNA, U6 small nuclear 1282, pseudogene)
Gene: Small nuclear RNA gene on chromosome 4 (151,300,518 to 151,300,613, forward strand). Ensembl gene ENSG00000252544.
Homologues: Orthologues: chimpanzee U6 (100% identical), mouse Gm23794 (84% identical). Paralogues in human: RNU6-1060P (90% identical), RNU6-15P (89% identical), RNU6-166P (89% identical), RNU6-41P (89% identical), RNU6-47P (89% identical), RNU6-517P (89% identical), RNU6-641P (89% identical), RNU6-1042P (88% identical), RNU6-116P (88% identical), RNU6-25P (88% identical), RNU6-33P (88% identical), RNU6-393P (88% identical), and 1288 more.